CBX3 (chromobox 3)
Diseases named in the same sentence as CBX3 in open-access papers (continued):
Sharing a sentence is not in itself a finding about the gene and the disease.
lung carcinoma (continued). "Specifically, the dissimilar roles of CBX3 could be reexamined to gain a greater insight into lung cancer pathogenesis." (PMID 39272883, 2024). "However, the involvement of CBX3 in lung cancer, and particularly its relationship with the Notch signaling pathway, remains relatively understudied and seems to present a more complex scenario." (PMID 39272883, 2024). "CBX3 regulates the Wnt/β-catenin signaling pathway, essential for cell proliferation, differentiation, and tumorigenesis in several types of cancer, including lung cancer." (PMID 39272883, 2024). "Interestingly, bioinformatic analysis revealed that among the eight CBX family members, only CBX3 was upregulated in both smoking-related pancreatic cancer and lung cancer." (PMID 35637952, 2022). "In breast and lung cancer over expression of CBX3 leads to poor prognosis." (PMID 34722422, 2021). "Furthermore, the development of small molecules specifically designed to inhibit CBX3 could represent a breakthrough in lung cancer treatment." (PMID 39272883, 2024). "Recent studies have demonstrated that overexpression of CBX3/HP1γ negatively impacts prognosis by promoting cancer development and growth in osteosarcoma, prostate cancer, colon cancer, pancreatic cancer, tongue squamous cell carcinoma, breast cancer, and lung cancer." (PMID 31375643, 2019). "It has been observed that CBX3 interacts with and potentially enhances the stability of MDM2 in lung cancer cells, inhibiting its auto-ubiquitination." (PMID 39272883, 2024). "In lung cancer, and especially in NSCLC, CBX3 appears to act primarily as an oncoprotein, promoting tumor growth and progression." (PMID 39272883, 2024). "In the case of lung cancer, specifically non-small cell lung cancer (NSCLC), CBX3 acts as an epigenetic oncoprotein, promoting the growth and progression of tumors." (PMID 39272883, 2024). "Based on the fact that knockdown of CBX3 results in an upregulation of FBP1 in pancreatic cells and upregulation of FOXM1 results in a decrease in FBP1 expression in lung cancer, it seems the simulation is indeed correct." (PMID 35404841, 2022). "In lung cancer, the expression of CBX1, CBX2, CBX3, and CBX5 was up-regulated, while CBX7 was down-regulated." (PMID 34966411, 2021). "Similar to CBX3, over-expression of CBX5 was found in many kinds of malignancies, such as pancreatic cancers, breast cancers and lung cancers." (PMID 30481161, 2018). "At present, no research has been conducted about the pathways CBX3 involved in the lung cancer, and our prediction is worth further verification through in vitro experiments." (PMID 32894652, 2020). "Thus, interventions aimed at inhibiting CBX3 could not only attenuate MAPK pathway hyperactivation but also impede the broader oncogenic network, providing a multifaceted approach to lung cancer therapy." (PMID 39272883, 2024).
glioma (19 papers, 2019 to 2025). A benign or malignant brain and spinal cord tumor that arises from glial cells (astrocytes, oligodendrocytes, ependymal cells). "Aberrant CBX3 expression has been associated with tumor progression in several cancer types, including glioma and gastric cancer." (PMID 39545414, 2024). "Although researchers have identified various proliferation-associated biomarkers as prognostic indicators for glioma patients, such as Par6, chromobox protein homolog 3 (CBX3) and nucleolar and spindle-associated protein 1 (NUSAP1), none of them has been routinely applied in clinical practice." (PMID 33712571, 2021). "CBX3 has been suggested to increase glioma growth by repressing transcription of E3 ubiquitin ligases that target epidermal growth factor receptor (EGFR)." (PMID 39545414, 2024). "The remaining mice were randomized to receive CT2A murine glioma cells transduced with either an shRNA control (shCONT) or Cbx3-targeting shRNA (shCbx3_1)." (PMID 39545414, 2024). "Next, we explored the role of CBX3 in vivo with an intracranial murine glioma line (CT2A) grown in a syngeneic host." (PMID 39545414, 2024). "For example, lncRNA LINC00998 can suppress the malignant glioma phenotype via the chromobox 3 (CBX3)-mediated c-Met/Akt/mTOR axis." (PMID 35156508, 2022). "CBX3 promotes cell proliferation and predicts poor prognosis in glioma, and P4HA1 is a biomarker of unfavorable prognosis in malignant melanomas." (PMID 34221975, 2021). "Collectively, these results demonstrated that knockdown of CBX3 reversed LINC00998 overexpression-mediated suppression of malignant phenotypes of glioma cells and Akt/mTOR signaling pathway key protein phosphorylation levels." (PMID 33268783, 2020). "Considering that there is little research about CBX3 in gliomas, we selected CBX3 for further study." (PMID 31138312, 2019). "In vitro enzymatic assays have demonstrated that CBX3 selectively potentiates the lactylation activity of P300 over its acetylation activity; notably, CBX3 is also currently the most well-documented lactylation ‘reader’ within the context of glioma." (PMID 41463052, 2025). "High CBX3 expression promoted glioma proliferation by targeting CDKN1A." (PMID 36292141, 2022). "CBX3 has also been shown to regulate the c-Met/AKT/mTOR signaling pathway in glioma." (PMID 34785774, 2022). "CBX3 overexpression was previously shown to promote tumor progression and to predict worse survival of lung, gastric, pancreatic, breast, glioma, osteosarcoma, liver, and kidney tumors." (PMID 36361869, 2022). "In malignant brain tumors, previous studies showed that CBX3 could promote the growth of glioma cells and displayed a prognostic role for glioma patients in vitro and in vitro." (PMID 36034290, 2022). "Similarly, the silence of CBX3 can inhibit glioma cell proliferation by blocking the cell cycle in the G2/M phase." (PMID 35172803, 2022). "Knockdown of LINC00998 enables glioma cells to acquire high proliferation ability by regulating CBX3 and the c-Met/Akt/mTOR signaling pathway, which indicates that LINC00998 may provide a rationale for precision therapy in glioma patients." (PMID 33268783, 2020). "Moreover, we carried out IP assays in the three glioma cell lines using an anti-CBX3 antibody and detected the ubiquitin levels of CBX3 by western blotting." (PMID 33268783, 2020). "The TCGA database also showed that the mRNA level of CBX3 was significantly correlated with the overall survival time of patients with pancreatic cancer, hepatocellular carcinoma, prostate cancer, and glioma." (PMID 33273987, 2020). "Knockdown of CBX3 could reverse the inhibitory phenotypes or phosphorylation levels of Akt, mTOR and p70S6K caused by LINC00998 overexpression, which implied that CBX3 might be an essential protein for LINC00998 function in glioma." (PMID 33268783, 2020). "In glioma and glioma-stem-like cells, lncRNA RP11-279C4.1 enhances malignant phenotypes by targeting the miR-1273g-3p/CBX3 axis." (PMID 39695079, 2024).
glioma (continued). "Similar findings have been reported for glioma; high expression levels of HP1-γ (CBX3) are known to predict a worse prognosis." (PMID 34046352, 2021). "High CBX3 targets CDKN1A to promote the proliferation of U87 cells and predicts poor recurrence-free survival and OS in glioma patients." (PMID 34395271, 2021). "CBX3, GUCY1A3, and IFRD1 have been reported in relation to some tumors but have been studied little in glioma." (PMID 31138312, 2019). "Furthermore, the chromobox protein homolog 3 (CBX3), DEK proto-oncogene (DEK), and DEAD (Asp-Glu-Ala-Asp) box polypeptide 39B (DDX39B) transcripts and proteins were up-regulated in glioma versus normal brain tissues." (PMID 37762371, 2023). "High expression of CBX3 was observed in several cancers such as HCC and glioma and could accelerate cell proliferation." (PMID 35155439, 2022). "Mechanistically, LINC00998 prevented CBX3 ubiquitination and promoted tri-methylation of histone H3K9 in c-Met promoter region, further downregulated the c-Met/Akt/mTOR signaling pathway, and then attenuated glioma progression." (PMID 33268783, 2020). "Since LINC00998 binds to CBX3 and prevents CBX3 ubiquitination degradation, we investigated whether knockdown of CBX3 could reverse the LINC00998 overexpression-mediated suppression of malignant phenotypes of glioma cells." (PMID 33268783, 2020).
pancreatic cancer (19 papers, 2015 to 2025). "This study aimed to uncover the specific role and underlying mechanism of CBX3 in smoking-related pancreatic cancer." (PMID 35637952, 2022). "Reanalysis of RNA-Seq samples from pancreatic cancer cells led us to define that the CBX3 locus gives rise to mRNA that encodes a novel spliced form of the CBX3 locus, which we termed small HP1γ, sHP1γ." (PMID 32027651, 2020). "Chen etal. found that CBX3/HP1γ promoted cell cycle transition-associated tumor progression by suppressing FBP1 in pancreatic cancer." (PMID 31375643, 2019). "The abnormal upregulation of CBX3 was associated with poor prognosis in pancreatic cancer patients." (PMID 35637952, 2022). "Exposure to cigarette smoke extract was observed to cause an increase in the overexpression of YBX1, which subsequently led to the upregulation of CBX3 (Chromobox 3) in pancreatic cancer cells." (PMID 38255791, 2024). "Chromobox 3 appeared to play a role in enhancing the progression of pancreatic cancer, possibly by suppressing the expression of SMAD-specific E3 ubiquitin protein ligase 2 and promoting the activation of the TGFβ signaling pathway." (PMID 38255791, 2024). "CBX3 has been identified as a positive regulator of aerobic glycolysis and promotes growth by suppressing fructose-1,6-bisphosphatase 1 in pancreatic cancer." (PMID 35464847, 2022). "Altogether, these findings strongly suggest CBX3 as a promising therapeutic target in pancreatic cancer." (PMID 35637952, 2022). "CBX3 was found to play a key role in cancer progression by suppressing the expression of SMURF2 in pancreatic cancer." (PMID 35637952, 2022). "In conclusion, cigarette smoking upregulated CBX3 in pancreatic cancer cells and tissues and this abnormal upregulation was associated with poor prognosis." (PMID 35637952, 2022). "Future studies are required to explore novel mechanisms by which CBX3 promotes pancreatic cancer progression." (PMID 35637952, 2022). "Consistently, survival analyses of the ICGC dataset further supported CBX3 as a poor prognostic predictor in pancreatic cancer." (PMID 35637952, 2022). "We also revealed that CBX3 enhanced pancreatic cancer progression, likely by inhibiting the expression of SMAD specific E3 ubiquitin protein ligase 2 (SMURF2) and promoting the activation of TGF‐β signaling." (PMID 35637952, 2022). "The bioinformatic analysis indicated that Chromobox protein homolog 3 (CBX3) had a close relationship with tobacco-induced pancreatic cancer." (PMID 35637952, 2022). "To this end, we constructed pancreatic cancer cells with stable knockdown for CBX3, SMURF2, or both together." (PMID 35637952, 2022). "Prior studies have demonstrated that CBX3 was overexpressed in GC, pancreatic cancer, HCC, osteosarcoma, CRC, prostate cancer and non-small cell lung cancer (NSCLC)." (PMID 36140750, 2022). "Our findings revealed that cigarette smoking induced the overexpression of CBX3 in pancreatic cancer cells and tissues, which consequently suppressed the expression of SMURF2 and enhanced the malignant potential of pancreatic cancer." (PMID 35637952, 2022). "Consistently, YBX1 was obviously upregulated by CSE exposure in pancreatic cancer cells, suggesting a potential role of YBX1 in smoking-induced CBX3 expression in pancreatic cancer." (PMID 35637952, 2022). "Subcutaneous injection of pancreatic cancer cells in mice was performed to study the role of CBX3 in vivo." (PMID 35637952, 2022). "As CBX3 overexpression was a poor prognostic predictor, we next evaluated the biological characteristics of CBX3 in pancreatic cancer cells." (PMID 35637952, 2022). "Herein, this study was conducted to investigate the pivotal roles and potential mechanisms of CBX3 in smoking-related pancreatic cancer." (PMID 35637952, 2022). "The bioinformatics analyses were conducted to identify CBX3 as a key player in tobacco-induced pancreatic cancer." (PMID 35637952, 2022).
pancreatic cancer (continued). "Another recent study demonstrates the role of CBX-3 in tumor progression in pancreatic cancer cell lines." (PMID 31565104, 2019). "Bioinformatic analysis indicated that upregulated CBX3/HP1γ expression predicts poor prognosis in liver cancer, breast cancer, pancreatic cancer, and renal cancer (Kaplan-Meier plot, log-rank test, all P values< 0.001)." (PMID 31375643, 2019). "Previous research has reported that silencing CBX3 could inhibit aerobic glycolysis in pancreatic cancer by enhancing the expression of FBP1, a negative regulator of aerobic glycolysis." (PMID 39636180, 2024). "Additionally, CBX3 was significantly overexpressed in almost all of the 20 cancers showed in the figure, except for liver cancer, pancreatic cancer and leukemia." (PMID 36140750, 2022). "Moreover, bioinformatic analyses indicated a positive correlation between YBX1 and CBX3 in the mRNA level in various cancers, including pancreatic cancer." (PMID 35637952, 2022). "Conversely, CBX3 overexpression promoted proliferation and invasion of pancreatic cancer cells." (PMID 35637952, 2022). "Moreover, cigarette smoke extract (CSE) exposure promoted the overexpression of Y-box-binding protein 1 (YBX1), which consequently led to upregulated CBX3 in pancreatic cancer cells." (PMID 35637952, 2022). "We found that Y-box binding protein 1 (YBX1), as a smoking-related protein 17 and oncogenic driver 18, could enhance the transcription of CBX3 in pancreatic cancer cells." (PMID 35637952, 2022). "Furtherly, CBX3 could promote cell proliferation through the suppression of SMAD specific E3 ubiquitin protein ligase 2 (SMURF2) in pancreatic cancer." (PMID 35637952, 2022). "Moreover, CSE-induced YBX1 overexpression contributed to the upregulation of CBX3 in pancreatic cancer cells." (PMID 35637952, 2022). "As a tumor promoter upregulated by smoking, CBX3 may be an ideal target for clinic treatment of pancreatic cancer." (PMID 35637952, 2022). "CBX3 promotes cancer cell proliferation by inhibiting the FBP1 gene in pancreatic cancer cells." (PMID 35573019, 2022). "Importantly, only CBX3 was consistently overexpressed and correlated with poor prognosis in patients with pancreatic cancer." (PMID 35637952, 2022). "Moreover, further MTS assay and Transwell assay indicated that YBX1 promoted pancreatic cancer cell proliferation and invasion by upregulating CBX3." (PMID 35637952, 2022). "Notably, the high expression of CBX3 was correlated with poor prognosis (disease free survival and overall survival) in pancreatic cancer patients from the TCGA dataset." (PMID 35637952, 2022). "CBX3 knockdown inhibited pancreatic cancer cell proliferation and invasion." (PMID 35637952, 2022). "Moreover, the expression of CBX3 were higher in pancreatic cancer cell lines than normal human pancreatic duct epithelial cells (HPDE6-C7)." (PMID 35637952, 2022). "In summary, the YBX1/CBX3/SMURF2 signaling axis may be a promising therapeutic target in patients with smoking-related pancreatic cancer." (PMID 35637952, 2022). "Similarly, in pancreatic cancer, CBX3 was reported to promote cell proliferation and regulate aerobic glycolysis by suppressing FBP-1." (PMID 36140750, 2022). "In terms of the cell cycle, CBX3 has been proved to promote G1/S cell cycle transition in tongue squamous cell carcinoma and colon cancer and has been shown to arrest the cell cycle in the G2/M phase in malignant gliomas and pancreatic cancers." (PMID 33273987, 2020). "In this study, we aimed to explore the expression and function of CBX3 in pancreatic cancer." (PMID 29903985, 2018). "Therefore, the YBX1/CBX3/SMURF2 signaling axis may be considered as a promising target for the treatment of smoking-related pancreatic cancer." (PMID 35637952, 2022). "However, the specific regulatory function and mechanism of CBX3 in smoking-related pancreatic cancer remain unknown." (PMID 35637952, 2022).
pancreatic cancer (continued). "To date, the relationship between CBX3 and smoking in pancreatic cancer remains unknown." (PMID 35637952, 2022). "In pancreatic cancer, YBX1 interacts with the epigenetic regulator CBX3 to promote cancer progression by inhibiting the expression of SMAD specific E3 ubiquitin protein ligase 2 (SMURF2) and activating TGF-β signaling." (PMID 40799245, 2025). "In conclusion, molecules such as RUNX2, CBX3, and MYC interact with YBX1 to promote tumor progression in various malignant tumors, including bone cancer, pancreatic cancer, and rhabdomyosarcoma, among others." (PMID 40799245, 2025). "CBX3 promoted malignant progression partly by inhibiting the expression of SMURF2 and activating the TGF-β pathway in pancreatic cancer." (PMID 35637952, 2022). "As CBX3 was found to repress SMURF2 expression, we then evaluated the relevance of SMURF2 in CBX3-induced pancreatic cancer progression." (PMID 35637952, 2022). "Taken together, our results indicate that CBX3 suppresses SMURF2 expression and activates the TGF-β pathway in pancreatic cancer." (PMID 35637952, 2022). "CBX3 has been found to be highly expressed and promote aerobic glycolysis by suppressing FBP1 in pancreatic cancer." (PMID 35210369, 2022). "The ChIP-qPCR analysis also revealed the binding of CBX3 and H3K9me3 to the promoter region of SMURF2 in pancreatic cancer cells." (PMID 35637952, 2022). "Collectively, these results demonstrate that YBX1 upregulates CBX3, which consequently represses SMURF2 and activates the TGF-β signaling pathway and promotes malignant progression in pancreatic cancer." (PMID 35637952, 2022). "In pancreatic cancer, NFATc2 binding to p15 promoter recruits histone methyltransferase Suv39H1 resulting in H3K9 trimethylation, which allows docking of CBX3 to the repressor complex giving rise to p15 silencing." (PMID 28193906, 2017). "Moreover, we detected the expression of CBX3 and SMURF2 in tissue microarrays from pancreatic cancer biopsies (n = 91)." (PMID 35637952, 2022). "We also analyzed the clinical relevance of CBX3 and other CBX family members in pancreatic cancer." (PMID 35637952, 2022). "CBX3 ablation simply upregulated the expression of SMURF2 but not SMURF1 in pancreatic cancer cells." (PMID 35637952, 2022). "Additionally, GSEA based on the datasets ICGC-PACA (Pancreatic Cancer)-AU (Australia), ICGC-PACA-CA (Canada) and CPTAC-PDAC also demonstrated that CBX3 played an essential role in activating the TGF-β signaling pathway in pancreatic cancer." (PMID 35637952, 2022). "We divided patients with pancreatic cancer into three groups: current smokers, former smokers, and never smokers, and found that CBX3 was markedly increased in current smokers (P < 0.05)." (PMID 35637952, 2022). "These increasing lines of evidence have suggested the important role of CBX3 in the progression and treatment of human cancers, however, the expression and mechanism of action of CBX3 in pancreatic cancer has not yet been fully understood." (PMID 29903985, 2018). "In addition, CBX3 and ABCC4 are promising therapeutic targets in osteosarcoma and pancreatic cancer, respectively." (PMID 26179909, 2015). "Furthermore, SMURF2 but not SMURF1 was downregulated in CBX3-overexpressed pancreatic cancer cells." (PMID 35637952, 2022). "In this study, we demonstrated that CBX3 downregulated SMURF2 but not SMURF1, consistent with the biological function of CBX3 in pancreatic cancer." (PMID 35637952, 2022). "It is worth noting that the mRNA levels of CBX1, CBX3, CBX5 and CBX8 were elevated in pancreatic cancer tissues compared with non-malignant pancreatic tissues." (PMID 35637952, 2022). "Consistently, simultaneous silencing of CBX3 and SMURF2 in pancreatic cancer cells did not restore the ability of tumor growth in vivo." (PMID 35637952, 2022).